EMCN (endomucin)
Diseases named in the same sentence as EMCN in open-access papers (continued):
Sharing a sentence is not in itself a finding about the gene and the disease.
tumor (continued). "Consequently, the IHC analysis of the tumor sections confirmed a reduction in the endomucin staining, which marks endothelial cells, in SVZ-vIII but not in GL261 tumors in the presence of the drug." (PMID 40157890, 2025). "The role of AGER role in tumor angiogenesis could be influencing EMCN expression in endothelial cells, thereby affecting tumor microenvironment and vascularization, which is critical for tumor growth and metastasis." (PMID 40535574, 2025). "EMCN regulates the permeability of blood vessels and may have implications for inflammation and tumour growth." (PMID 38332687, 2024). "The number of endomucin-expressing endothelial cells in tumor tissue was decreased in the GANT61-treated group, and the number of endomucin-expressing endothelial cells in tumor tissue per unit area was significantly decreased in the GANT61-treated group compared to the control group (p < 0.05)." (PMID 37240209, 2023). "Herein, we report a new mechanism by which EMCN deficiency leads to tumor metastasis independent of tumor growth." (PMID 36184589, 2022). "These analyses revealed an important role of EMCN in the progression of tumor metastasis." (PMID 36184589, 2022). "Therefore, we demonstrated the important role of EMCN deletion in endothelial cell infiltration and tumor premetastatic niche formation." (PMID 36184589, 2022). "Comparative experiments in WT and EMCNecko mice revealed that endothelial EMCN deficiency did not affect primary tumor growth significantly but strongly promoted spontaneous metastasis." (PMID 36184589, 2022). "A proteomic analysis of colorectal normal and tumor ECM revealed that collagen IV, V and XIV, fibrilin, emilin, vitronectin, laminin and endomucin have increased expression in tumor ECM, and that periostin, versican, thrombospondin-2 and tenascin were exclusively present in tumor tissue." (PMID 35053521, 2022). "Endomucin (EMCN) was overexpressed in tumor tissues compared to normal para‐carcinoma tissues." (PMID 35971319, 2022). "Future in‐depth studies of the relationship between endomucin and angiogenesis in tumor invasion and metastasis may suggest new targets for clinical anti‐angiogenesis therapy." (PMID 33532708, 2020). "Finally, we examined the distribution of tumour cells in the brain by co-staining sections with the endothelial markers endomucin and CD31, and an antibody against human lamin A/C to detect the MDA-MB-231-Luc cells." (PMID 30642388, 2019). "Similarly, numerous endomucin-positive cells were observed bothin control and vehicle-treated tumours, whereas in DHS treated mice, few redspots were detectable in the tumour masses." (PMID 26829331, 2016). "Importantly, immunostaining of a day 13 primary tumor for endosialin and the endothelial marker endomucin revealed endosialin+ stromal cells throughout the tumor bed closely associated with the vasculature, indicating that the E3K CAR-T cell target is well expressed in developing tumors." (PMID 38413223, 2024). "However, compared with EMCNecko mice, anti-TGF-β antibody did not affect tumor growth but inhibited lung metastasis caused by EMCN deletion." (PMID 36184589, 2022). "We hypothesized that EMCN downregulation may be important for tumor metastasis and recurrence." (PMID 36184589, 2022). "The results showed that ccRCC cells co-cultured with EMCN-silenced HUVECs exhibited significantly enhanced proliferation compared to the control group, indicating that EMCN knockdown in endothelial cells may promote tumor growth by modulating the tumor microenvironment." (PMID 40535574, 2025). "We stained two sequential tumor sections – one using IHC for TMEM doorways (Iba1, Endomucin, Mena) and the second using IF for CSF-1, dextran, and endothelial cells (endomucin) and aligned the images of stained sections to the single cell level." (PMID 40646332, 2025). "The hypermethylated pattern identified in the promoters of EC markers CD34, EMCN, and TEK suggests a downregulated expression in tumor tissues." (PMID 39103878, 2024).
tumor (continued). "The top five differential genes in LumB tumours, ranked by significance, are MIS18A, WIF1, CHEK2, EMCN and CDK4." (PMID 38332687, 2024). "As NRP1flflNRP2flfl.ECKO tumor vessels exhibited significantly reduced EDA-FN outgrowth, we subsequently assessed pericyte coverage by co-immunolabeling NG2+ mural cells with endomucin+ blood vessels." (PMID 36970722, 2022). "Nevertheless, the expression of ANGPT2, EMCN and ZNF532 genes was significantly higher in the HCC tumor samples compared to the normal liver tissue samples." (PMID 32644941, 2020). "The atypical mucins mRNA (MUC14/EMCN and MUC18/MCAM) were also increased in tumor samples (p < 0.01)." (PMID 33182511, 2020). "We also found that the expression of these 5 genes, namely, ANGPT2, EMCN, GLDN, USHBP1 and ZNF532, was significantly upregulated in HCC tumor tissues compared to the adjacent normal liver tissues in the TCGA and ICGC datasets." (PMID 32644941, 2020). "We observed for the first time a patient subgroup that is characterized by a higher expression of MUC14/EMCN, MUC18/MCAM, and MUC15 in their tumor tissue." (PMID 33182511, 2020). "GLUT1 expression, indicative of glycolysis induction, was particularly prominent in tumor areas lacking vasculature, revealed by immunofluorescence (IF) using antibodies against an endothelial marker endomucin, especially in Tie2e-Tert-KO mice." (PMID 40482194, 2025). "To determine the impact of inhibition of tumor cell-derived CSF-1 inhibition on the levels of VEGF-A expression in TMEM doorway macrophages in vivo, we stained the tumors for VEGF-A, F4/80 to identify macrophages, and endomucin." (PMID 40646332, 2025). "To assess whether changes in the colonization niche were different between tumor types, we stained bones for Sca-1+ HSC cells and endomucin+ blood vessels." (PMID 38136319, 2023). "We therefore examined whether VEGFR-2 signaling would be perturbed in tumor vasculature depleted for NRP1 and NRP2 by measuring VEGFR-2 and phosphorylated-VEGFR-2Y1175 localization to endomucin+ vessels." (PMID 36970722, 2022). "Interestingly, compared to the regularly shaped PyMT tumor vessels, which displayed colocalized lectin-TRITC with endomucin-FITC in most vessels (SIAppendix), GPx2 KD tumor vessels were devoid of lectin-TRITC at the endothelial cell membrane." (PMID 35193955, 2022). "This challenge becomes further exacerbated when we consider that EMCN is not expressed on tumor cells but on normal endocytic endothelial cells." (PMID 36184589, 2022). "We found that EMCN was overexpressed in tumor tissues compared with that in normal para‐carcinoma tissues." (PMID 35971319, 2022). "The perfusion ratio or the fraction of endomucin-FITC+ vessels colocalizing with lectin-TRITC, was significantly reduced in GPx2 KD tumors relative to controls, suggesting GPx2 KD in tumor cells impairs vascular perfusion." (PMID 35193955, 2022). "In the in vivo study, we found that EMCN did not affect angiogenesis but did affect tumor metastasis." (PMID 36184589, 2022). "Interestingly, MUC14/EMCN, which is described as an endothelial mucin, was expressed by tumor cells." (PMID 33182511, 2020). "Parraffin-embedded sections of 16 tumours generated from PTRF-expressing or control PC3 cells were analysed by immunofluorescence using the lymphatic-specific marker podoplanin and the panendothelial cell marker endomucin." (PMID 24123650, 2013). "CLEC14a, EMCN, and ADM5 were further validated in the single-cell Curated Cancer Cell Atlas (3CA) to be highly specific to the endothelial cell clusters across multiple tumor types, while IGFBP4 was diversely expressed in endothelial, fibroblast, and some malignant cell types." (PMID 41776551, 2026). "Whether endomucin affects the adhesion between tumor cells and endothelial cells has not been reported." (PMID 33532708, 2020). "However, DMOG treatment of 4T1 tumour‐bearing mice did not alter the area of endomucin‐positive blood vessels (Fig EV4D)." (PMID 26323721, 2015).
tumor (continued). "Consequently, EMCN expression in ECs does not affect tumor growth in vivo." (PMID 36184589, 2022). "As was expected for anti-angiogenic therapies, treatment with r84 and bevacizumab resulted in a significant decrease in tumor MVD as demonstrated using two endothelial cell markers, MECA-32 (data not shown) and endomucin." (PMID 20700512, 2010).
cancer (17 papers, 2010 to 2026). A tumor composed of atypical neoplastic, often pleomorphic cells that invade other tissues. "In conclusion, we demonstrate that EMCN deficiency in endothelial cells promotes metastasis by providing a suitable premetastatic niche for cancer cell extravasation and lung colonization." (PMID 36184589, 2022). "EMCN/MUC15 top 50 correlated genes were identified to be enriched in cancer-related processes, including vasculature development, mitosis, immunity, and so on." (PMID 32175327, 2020). "EMCN/MUC15 correlated genes were identified to be enriched in cancer-related processes, such as vasculature development, mitosis, and immunity." (PMID 32175327, 2020). "CLEC14a and EMCN were validated as TEC markers, extending their annotation in breast TEC, and ADM5 identified as a novel TEC marker in breast and other cancers." (PMID 41776551, 2026). "The results showed that TPX2 and BIRC5 were upregulated, while AGER, TEK, CLIC5, MAMDC2, EMCN, and SEMA3G were mostly downregulated in multiple cancer types." (PMID 40535574, 2025). "These indicate that genes correlated with EMCN and MUC15 in GC tend to be enriched in cancer related processes, such as vasculature development, mitosis, and immunity." (PMID 32175327, 2020). "Two additional atypical endothelial mucins (MUC14/EMCN and MUC18/MCAM) have been described in cancer." (PMID 33182511, 2020). "We examined EMCN expression in CRC tissues and normal para‐carcinoma tissues." (PMID 35971319, 2022). "For examples, TNXB, SPP1 and EMCN have not previously been reported as cancer-related." (PMID 21060876, 2010).
infection (1 paper, 2017). The state of being infected such as from the introduction of a foreign agent such as serum, vaccine, antigenic substance or organism. "Exposure to AdEMCN resulted in a 10.6-fold increase in EMCN mRNA and an approximately 4-fold increase in protein at 24 and 48 hr after infection." (PMID 29215001, 2017).
EMCN also shares sentences with these, for which no sentence is quoted: esophageal cancer (2 papers); leukemia (2); atherosclerosis (1); bladder cancer (1); central nervous system lymphoma (1); cervical cancer (1); colon adenocarcinoma (1); diabetes (1); follicular carcinoma (1); follicular thyroid adenoma (1); head and neck cancer (1); hepatocellular carcinoma (1); hypertrophic cardiomyopathy (1); kidney cancer (1); liver cancer (1); lymphoma (1); metastatic cancers (1); pancreatic adenocarcinoma (1); stomach adenocarcinoma (1); triple-negative breast carcinoma (1); Wilms tumor (1).